RNU6-1222P (RNA, U6 small nuclear 1222, pseudogene)
Gene: Small nuclear RNA gene on chromosome 6 (148,278,672 to 148,278,778, forward strand). Ensembl gene ENSG00000207345.
Homologues: Orthologues: chimpanzee U6 (99% identical), mouse Gm56453 (67% identical), mouse Gm56396 (58% identical), mouse Gm55827 (57% identical). Paralogues in human: RNU6-338P (88% identical), RNU6-820P (88% identical), RNU6-140P (87% identical), RNU6-971P (87% identical), RNU6-1060P (86% identical), RNU6-1152P (86% identical), RNU6-1249P (86% identical), RNU6-19P (86% identical), RNU6-476P (86% identical), RNU6-49P (86% identical), RNU6-748P (86% identical), RNU6-949P (86% identical), and 1289 more.